CYP17A1 (cytochrome P450 family 17 subfamily A member 1)
Diseases named in the same sentence as CYP17A1 in open-access papers (continued):
Sharing a sentence is not in itself a finding about the gene and the disease.
atherosclerosis (4 papers, 2020 to 2025). A disease characterized by the build-up of fatty material and calcium deposition in the arterial wall resulting in partial or complete occlusion of the arterial lumen. "Previous studies have also demonstrated an association between some CYP family members (CYP7A1 and CYP17A1), gut bacteria, and atherosclerosis." (PMID 34070975, 2021). "To understand the mechanisms underlying the association between low testosterone and atherosclerosis, we tested the effects of CYP17A1-deficiency on lipid metabolism, as a plausible contributor to atherosclerosis in our mouse model." (PMID 32472014, 2020). "Together, these results demonstrate that ablation of CYP17A1 accelerates vascular endothelial injury and promotes the formation of atherosclerosis in a time and diet–dependent manner." (PMID 37370070, 2023). "In the present study, we aimed to determine the effects of diet and Cyp17a1 genotype on the composition of the microbiota in a mouse model of atherosclerosis (ApoE KO)." (PMID 34070975, 2021). "Surprisingly, no changes in atherosclerosis development were detected in XX Cyp17a1 KO mice, although previous studies reported enhanced atherosclerosis in castrated females." (PMID 32472014, 2020). "The animal plasma steroid analyses revealed the hypothesis completely that CYP17A1 may related to atherosclerosis by participating in the regulation of steroid." (PMID 37370070, 2023). "To test the expression of CYP17A1 in human materials we conducted gene expression analysis in different cell lines that play a role during the initiation and development of atherosclerosis such as monocytes, aortic smooth muscle cells (HASMCs) and endothelial cells (HUVECS)." (PMID 32472014, 2020). "In this context, we generated CYP17A1-deficient mice and studied the impact of lack of this gene on steroid metabolism, as well as its roles in atherosclerosis and lipid metabolism." (PMID 32472014, 2020). "Increased atherosclerosis in CYP17A1 XY KO mice lacking testosterone was associated with altered lipid profiles." (PMID 32472014, 2020). "We aimed to investigate the function of CYP17A1 and its impact on atherosclerosis in mice." (PMID 32472014, 2020). "Nevertheless, the data support the conclusion that Cyp17a1 promotes atherosclerosis in male mice, but not in female mice, regardless of diet type, which aligns with observations in human studies." (PMID 40268998, 2025). "In addition, Cyp17a1 heterozygous mice were also backcrossed onto an Apoe KO atherogenic background and fed a western-type diet (WTD) to study the effects of CYP17A1 on atherosclerosis." (PMID 32472014, 2020). "Furthermore, a significant lipid infiltration in the intima of vessels of CYP17A1−/− compared to the WT with HFD, not observed in the chow, suggesting CYP17A1 gene may interact with high-fat diet, which play together in the occurrence and development of atherosclerosis." (PMID 37370070, 2023).
glioblastoma (4 papers, 2019 to 2023). The most malignant astrocytic tumor (WHO grade IV). "Interestingly, the level of SRP14 protein in glioblastoma cells is increased by CYP17A1, an enzyme implicated in steroidogenesis." (PMID 36361638, 2022). "In addition to steroid hormone synthesis, CYP17A1 associates with SAR1a/b to regulate protein processing and maintain ER health in glioblastomas." (PMID 31527549, 2019). "Previously, we showed that CYP17A1 upregulation confers drug resistance to glioblastomas by increasing DHEA synthesis." (PMID 31527549, 2019). "Previously, we clarified that CYP17A1-mediated DHEA synthesis is important for glioblastomas to develop drug resistance against temozolomide (TMZ) treatment." (PMID 31527549, 2019). "Based on the current and previous findings, blockade of CYP17A1 activity is a potential strategy to suppress glioblastomas." (PMID 31527549, 2019). "By regulating secretion-associated Ras-related GTPase (SAR) 1 expression, which is important for the process of protein trafficking from the ER to the Golgi apparatus, CYP17A1 is required for the survival of glioblastomas." (PMID 31527549, 2019). "Previously, we showed that CYP17A1-mediated DHEA production clearly protects glioblastomas from temozolomide-induced apoptosis, leading to drug resistance." (PMID 31527549, 2019). "A strategy targeting steroidogenesis, such as the inhibition of CYP17A1, is a potential option for glioblastoma treatment." (PMID 31527549, 2019). "Abiraterone, an inhibitor of CYP17A1, significantly inhibits the proliferation of A172, T98G, and PT#3 (the primary glioblastoma cells) by inducing apoptosis." (PMID 31527549, 2019). "It has been reportedthat CYP17A1 is overexpressed in some forms of glioblastoma." (PMID 37191389, 2023). "Herein, we attempt to clarify whether the inhibition of CYP17A1 has a tumor-suppressive effect, and to determine the steroidogenesis-independent functions of CYP17A1 in glioblastomas." (PMID 31527549, 2019). "Therefore, the inhibition of CYP17A1 by abiraterone exhibited an obvious tumor-suppressive effect on glioblastomas in vitro and in vivo." (PMID 31527549, 2019). "Hence, we aimed to study whether abiraterone, a well-known CYP17A1 inhibitor, potentially suppresses glioblastomas." (PMID 31527549, 2019). "However, to further demonstrate whether CYP17A1-mediated steroidogenesis contributes to gender differences, the levels of multiple steroid hormones in both male and female glioblastomas will be globally estimated in the future." (PMID 31527549, 2019). "Herein, we identified a novel function of CYP17A1 that is independent of steroidogenesis, and showed that CYP17A1 maintains the survival of glioblastomas by regulating SAR1a/b-mediated protein processing in the ER." (PMID 31527549, 2019). "Therefore, we think that CYP17A1 is not involved in gender differences of glioblastoma." (PMID 31527549, 2019).
lung carcinoma (4 papers, 2012 to 2024). "A total of 83 potential targets of ROB in lung cancer were collected and further screened by using Cytoscape software, and 7 targets of PTGS2, CYP19A1, PTGS1, AR, CYP17A1, PTGES and SRD5A1 were obtained as hub genes and 7 hub targets had good binding energy with ROB." (PMID 39450260, 2024). "The hub targets of ROB action in lung cancer were further analyzed by combining 14 targets from Degree≥6, 10 targets each from MCC and MNC algorithms, and finally 7 common targets such as PTGS2, CYP19A1, PTGS1, AR, CYP17A1, PTGES and SRD5A1 were obtained from the final screening." (PMID 39450260, 2024).
neuroblastoma (4 papers, 2020 to 2025). Neuroblastoma (NB) is the most common solid, extracranial childhood tumor. "It is still unknown that whether the expression of the six genes, AR, SCAP, SREBF1, SREBF2, HMGCR, and CYP17A1 are closely associated with neuroblastoma patient survival." (PMID 34041015, 2021). "Targeting AR-SCAP-SREBPs-HMGCR/CYP17A1 axis will provide a novel strategy for neuroblastoma treatment." (PMID 34041015, 2021). "The results suggested that combined HMGCER and CYP17A1 inhibition synergistically restrained neuroblastoma proliferation and this strategy showed good safety." (PMID 34041015, 2021). "In spite of too limited ganglioneuroblastoma (GNB) specimens were acquired, the activation of this AR-SCAP-SREBPs-HMGCR/CYP17A1 axis was specific in NB distinct from other neuroendocrine or neuroblastic tumors." (PMID 34041015, 2021). "The downregulation of CYP17A1 may be an indicator of poor prognosis in neuroblastoma." (PMID 33245713, 2020). "Although the function of AR in neuroblastoma cells were investigated in the previous work, the expression of AR and other proteins in AR-SCAP-SREBPs-CYP17A1/HMGCR Axis had never been examined in clinical samples of neuroblastoma or other types of neuroblastic or neuroendocrine tumors." (PMID 34041015, 2021). "In our study, MYCN-non-amplified human neuroblastoma cells, SH-SY5Y, were quite sensitive to the HMGCR and CYP17A1 inhibitors in vitro and in vivo, whereas SK-N-BE, a MYCN-amplified human neuroblastoma cell line, were also suppressed by the two inhibitors in combination in vitro." (PMID 34041015, 2021).
osteoporosis (4 papers, 2019 to 2023). A condition of reduced bone mass, with decreased cortical thickness and a decrease in the number and size of the trabeculae of cancellous bone (but normal chemical composition), resulting in increased fracture incidence. "The deficiency of CYP17A1 can result in reduced growth and osteoporosis." (PMID 30641909, 2019).
17-alpha-hydroxylase deficiency (3 papers, 2019 to 2025). "Both siblings presented the CYP17A1 c.1246C>T; p.(Arg416Cys) variant in homozygosis, which has been previously associated with 17-alpha-hydroxylase deficiency and explains the phenotype." (PMID 39596125, 2024). "Two patients had variants in HSD17B3 and CYP17A1 genes, resulting in 17-beta hydroxysteroid dehydrogenase III (17βHSD-3) deficiency and 17-alpha hydroxylase deficiency (17OHD), respectively." (PMID 39936125, 2025).
21-hydroxylase deficiency (3 papers, 2023 to 2025). "Although pathogenic variants have been identified in several genes, including CYP11B1, CYP17A1, HSD3B2, POR, STAR, and CYP11A1, approximately 95% of CAH cases are caused by 21-hydroxylase deficiency (21-OHD), primarily due to mutations in the CYP21A2 gene." (PMID 41440812, 2025).
adrenocortical tumors (3 papers, 2020 to 2025). "Thus, our aim was to analyze the expression profile of four key proteins involved in the steroidogenesis cascade, namely StAR protein, CYP11B1, CYP11B2 and CYP17A1, in different types of adrenocortical tumors." (PMID 32751564, 2020).
Cushing syndrome (3 papers, 2019 to 2022). Cushing's syndrome (CS) encompasses a group of hormonal disorders caused by prolonged and high exposure levels to glucocorticoids that can be of either endogenous (adrenal cortex production) or exogenous (iatrogenic) origin. "However, we do not see the development of Cushing’s syndrome nor the switching on of Cyp17a1 in the adrenal cortex." (PMID 31320667, 2019).
diabetes (3 papers, 2005 to 2020). "Associations between three-site haplotypes in the cytochrome P450 family 17 subfamily A member 1 gene region and type 2 diabetes mellitus risk in Han Chinese participants." (PMID 29942286, 2018). "Here we focused on CYP17A1, a gene mapping to a locus associated with various cardiovascular disorders, including CAD, MI, diabetes, and arterial stiffness, according to GWAS3,33,34,38–40." (PMID 32472014, 2020). "Three tagging single nucleotide polymorphisms (rs1004467, rs17115149, and rs12413409), in the CYP17A1 gene region were selected and genotyped in a case–control study that included 440 diabetes and 1,320 control subjects." (PMID 29942286, 2018).
gastric cancer (3 papers, 2012 to 2022). A primary or metastatic malignant neoplasm involving the stomach. "The objective of the study was to investigate the role of genes (HSD3B1, CYP17A1, CYP19A1, HSD17B2, HSD17B1) involved in the steroid hormone biosynthesis pathway and progesterone receptor (PGR) in the etiology of gastric cancer in a population-based two-phase genetic association study." (PMID 23110082, 2012).
glioma (3 papers, 2017 to 2023). A benign or malignant brain and spinal cord tumor that arises from glial cells (astrocytes, oligodendrocytes, ependymal cells). "Among the target genes in MrGPS, CYP17A1 is up-regulated in gliomas, playing a role in mediating glioma cell invasiveness and contributing to resistance against TMZ-induced cytotoxicity." (PMID 38171932, 2023). "In particular, the upregulation of DHEA in gliomas is caused by Sp1-mediated cytochrome P450 (CYP) 17A1 overexpression, implying that CYP17A1 is a potential target for glioma treatment." (PMID 31527549, 2019). "In particular, the increase of CYP17A1 was caused by Sp1-mediated DNA demethylation, whereby Sp1 competed with DNMT3a for binding to the CYP17A1 promoter in TMZ-resistant glioma cells." (PMID 28530704, 2017). "To identify which transcription factor is a potent regulator for CYP17A1 transcription in glioma, we analyzed the correlation of CYP17A1 with NFIC, Sp1, Sp3 or GATA6 in complementary DNA microarray database of glioma." (PMID 28530704, 2017). "CYP17A1 was required for the development of glioma cell invasiveness and resistance to TMZ-induced cytotoxicity." (PMID 28530704, 2017). "In the present study, we found that CYP17A1 expression was significantly increased by Sp1 and correlated with poor prognosis in glioma patients." (PMID 28530704, 2017). "To investigate the role of CYP17A1 in glioma, we determined that CYP17A1 expression is significantly increased in gliomas, which secrete more DHEA than normal astrocytes." (PMID 28530704, 2017). "We found that as gliomas became more malignant, both CYP17A1 and DHEA were significantly upregulated in temozolomide (TMZ)-resistant cells and highly invasive cells." (PMID 28530704, 2017). "The upregulation of CYP17A1 mRNA correlated with glioma formation and prognosis." (PMID 28530704, 2017). "To elucidate whether Sp1-mediated CYP17A1 expression is involved in glioma development, we showed that Sp1 expression markedly increased as astrocytoma progressed to grade IV GBM and that Sp1 strongly promoted glioma invasion." (PMID 28530704, 2017). "Interestingly, CYP17A1 knockdown abolished Sp1-enhanced invasiveness, thus further suggesting that Sp1-mediated CYP17A1 expression is required for glioma malignancy." (PMID 28530704, 2017). "Therefore, further investigation is required to determine whether drugs targeting CYP17A1 may be useful for the treatment of glioma patients." (PMID 28530704, 2017). "Although pregnenolone exhibits a pro-apoptotic effect in glioma, its metabolite, DHEA, synthesized by CYP17A1, contributes to TMZ resistance." (PMID 28530704, 2017). "To determine whether the CYP17A1–DHEA axis is indeed involved in the process of glioma malignancy, we established more aggressive glioma cell lines that exhibited resistance to TMZ or became more invasive." (PMID 28530704, 2017). "In addition, whether CYP17A1, the key steroidogenic enzyme in DHEA biosynthesis, affects glioma malignancy, including invasion and drug resistance, is also unknown." (PMID 28530704, 2017). "However, whether CYP17A1-mediated DHEA synthesis is involved in brain tumor malignancy, especially in glioma, the most prevalent brain tumor, is unknown." (PMID 28530704, 2017).
male infertility (3 papers, 2018 to 2023). The inability of the male to effect fertilization of an ovum after a specified period of unprotected intercourse. "It has been associated with CYP17A1 RNA expression, and may represent a genetic risk factor for male infertility and testosterone levels." (PMID 29942286, 2018). "Intersection of genes from transcriptomic studies with genes with identified rare variants revealed a total of 7 genes linked with male infertility phenotype (CYP11A1, CYP17A1, RSPH3, TSGA10, AKAP4, CCIN, NDNF)." (PMID 37670815, 2023). "With this CYP17A1 cKO model they showed that NR5A1 depletion in Leydig cells of mature male mice can result in male infertility, whilst depletion of NR5A1 in theca cells of mature female mice mainly caused impaired steroidogenesis, with fertility being preserved." (PMID 37726790, 2023).
melanoma (3 papers, 2020 to 2023). A malignant, usually aggressive tumor composed of atypical, neoplastic melanocytes. "Human melanoma tissues represented a prominent steroidogenic tumor type, expressing CYP11A1, HSD3B1, HSD3B2, CYP17A1, CYP21A1, and CYP11B1 and not expressing CYP11B2." (PMID 32680985, 2020).
Asperger syndrome (2 papers, 2020 to 2024). "In the past, relation of polymorphism in gene coding CYP17A1 and Asperger syndrome was observed." (PMID 39636905, 2024). "Same, the association between AQ and Asperger syndrome and CYP17A1 was found." (PMID 33024080, 2020).
Follicular Cyst (2 papers, 2023). Cyst due to the occlusion of the duct of a follicle or small gland. "The Kyoto Encyclopedia of Genes and Genomes (KEGG) analysis linked the ovarian steroidogenesis pathway, especially the STAR, 3β-HSD, CYP11A1 and CYP17A1 genes, to the formation of follicular cysts (p < 0.01)." (PMID 37958056, 2023). "In this study, through transcriptomic analysis of TIMG cells, we found that StAR and CYP11A1, as well as CYP17A1 and 3β-HSD were significantly enriched in the signaling pathway of cortisol synthesis and secretion in follicular cysts." (PMID 38274662, 2023).
hypopituitarism (2 papers, 2016 to 2023). A condition of diminution or cessation of secretion of one or more hormones from the anterior pituitary gland. "Low E3 occurs on the presence of several other steroidogenic deficiency, such as steroidogenic acute regulatory protein deficiency, CYP17A1 deficiency, steroid sulfates deficiency, defects of placental aromatase, hypopituitarism, and Smith–Lemli–Opitz syndrome." (PMID 37635957, 2023).
Impaired glucose tolerance (2 papers, 2016 to 2023). An abnormal resistance to glucose, i.e., a reduction in the ability to maintain glucose levels in the blood stream within normal limits following oral or intravenous administration of glucose. "This study showed that Cyp17a1 mRNA level was significantly decreased in liver tissue of DHEA female offspring, which may be related to body weight gain, increased body fat and TG content or to impaired glucose tolerance." (PMID 27798284, 2016).
metastatic disease (2 papers, 2020 to 2024). "Six APUC genes (HSD3B1, HSD3B2, CYP3A43, CYP11A1, CYP11B1, CYP17A1) exhibited coalescent gene behavior in a cohort of metastatic tumors (n = 208)." (PMID 39207857, 2024). "Of the many APUC genes that have been associated with the activation of AR, we found that 6 (HSD3B1, HSD3B2, CYP11A1, CYP11B1, CYP17A1, and CYP3A43) exhibit robust association in prostate and metastatic tumors and were mutually exclusive with heightened AR activity." (PMID 39207857, 2024).
Ovarian Hyperandrogenism (2 papers, 2013 to 2021). Increased production of androgens by the ovaries. "PAE could reduce the excessive testosterone in theca cells through downregulation of CYP17A1 and CYP11A1, which provided scientific evidence for the treatment of ovarian hyperandrogenism with PAE." (PMID 33638949, 2021).
preeclampsia (2 papers, 2020 to 2024). Preeclampsia is a hypertensive disorder of pregnancy that is characterized by new-onset hypertension with proteinuria presenting after 20 weeks of gestation, and depending on mild or severe forms may initially present with severe headache, visual disturbances, and hyperreflexia. "By contrast, the 17-OHP-to-androstenedione ratio (both OHP and androstenedione are metabolized by the enzyme CYP17A1 in the testes, ovary or placenta) seems to be affected by preeclampsia, defined by a reduced ratio (p < 0.001)." (PMID 39684415, 2024). "We identified CYP17A1, HSD17B3, SRD5A1, CYP19A1, CYP11B1, HSD11B1 and HSD11B2 as potentially affected enzymes in preeclampsia." (PMID 39684415, 2024). "mRNA expressions of genes of enzymes with significantly decreased precursor-to-product ratios (i.e., CYP17A1, HSD17B3, CYP11B1 and HSD11B2) was similar in women with preeclampsia and controls, but the RNA levels of these genes were higher in women with preeclampsia." (PMID 39684415, 2024).
schizophrenia (2 papers, 2020 to 2022). A major psychotic disorder characterized by abnormalities in the perception or expression of reality. "CYP17A1 has previously been found to be associated with schizophrenia; our detected association is novel for MDD." (PMID 32373164, 2020). "DNAm within an exonic–intronic fragment of CYP17A1 was assessed in the blood of 66 schizophrenia patients and 63 controls using single-molecule real-time bisulfite sequencing." (PMID 36293479, 2022).
sterility (2 papers, 2024 to 2025). "This highlights the important role that Cyp17a1 plays in fertility as Cyp17a1−/− subjects’ continued deficiency resulted in sterility." (PMID 38804291, 2024).